INS (insulin)
Diseases named in the same sentence as INS in open-access papers (continued):
Sharing a sentence is not in itself a finding about the gene and the disease.
Hyperglycemia (continued). "Moreover, ICCs could respond to glucose stimulation and release insulin and C-peptide in vitro, and following implantation into diabetic mice, hyperglycemia was reversed." (PMID 32641151, 2020). "BGM may need to be performed up to 6–10 times per day to identify patterns or trends in order to adjust the insulin regimen, perform “real-time” correction of hyperglycemia, evaluate the impact of foods on postprandial glycemia, and confirm and treat hypoglycemia." (PMID 32256447, 2020). "In T2D, INSR becomes resistant to insulin cues for the activation of downstream signaling which controls hepatic glucose production (gluconeogenesis) and blood glucose clearance (primarily into skeletal muscle); this results in hyperglycemia and glucose intolerance." (PMID 31378829, 2020). "The improvement of hepatic insulin sensitivity of the exercised obese animals can be confirmed, due to the fact that these animals, even presenting a significant reduction of hyperinsulinemia, nonetheless tended to increase hepatic Akt phosphorylation and a significant reduction in hyperglycemia." (PMID 32847099, 2020). "Hyperglycemia causes a significant increase in lipid profile levels, which may be related to a lack of insulin." (PMID 32983244, 2020). "However, in IR animal models and in vitro models insulin target tissues (liver, muscle or adipose tissue) show reduced glucose uptake and glycogen synthesis and enhanced glucose de novo synthesis, thus contributing to aggravation of hyperglycemia." (PMID 33212990, 2020). "The elevated expression of CaV3.1 channels not only impairs both basal insulin release and first-phase glucose-stimulated insulin secretion with no influence on second-phase insulin response but also disables islets from normalizing hyperglycemia in STZ-induced diabetic rats." (PMID 31871187, 2020). "Moreover, hyperglycemia may, in turn, impair insulin sensitivity, resulting in a vicious circle toward IR." (PMID 32587566, 2020). "Therefore, it was improper to distinguish whether the elevated blood glucose was the reason for postoperative insulin therapy, while hyperglycemia could be considered as the most common reason in the study population." (PMID 32903325, 2020). "Some athletes will tolerate, or even plan for, a slightly elevated blood glucose level when starting an event; others may choose to use a temporary basal rate increase (if using CSII), a partial bolus insulin correction or a prolonged aerobic warm-up to correct hyperglycaemia." (PMID 32533229, 2020). "In addition to sensitizing insulin intracellular signaling, adropin may antagonize glucagon signaling pathway in reducing hyperglycemia." (PMID 32917052, 2020). "Future studies could explore the anabolic property of PTH in the DM condition when hyperglycemia is controlled with insulin, and immunolabeling or molecular analyses could be performed to further evaluate the possible anabolic activity of PTH and signaling pathways." (PMID 32348445, 2020). "Dual activity against α-glucosidase and PTP1B for compounds 2c, 2g and 2h would probably result in synergistic effects to prevent hyperglycaemia, in turn, effectively improving insulin sensitization without increasing lipid metabolism and causing lipid accumulation in livers." (PMID 32156083, 2020). "While the ultimate pathways responsible for the increased risk of dementia in T2D patients have not been elucidated, hyperglycemia, vascular alterations, impaired insulin signaling, and affected amyloid clearance have been pointed out as some of the most relevant underlying possibilities." (PMID 32264944, 2020). "In conclusion, L. paracasei HII01 alleviated hyperglycemia in diabetic rats primarily by modulating gut microbiota along with lessening leaky gut, leading to improvement in endotoxemia and inflammation-disturbed insulin signaling, which was mediated partly by PI3K/Akt signaling and AMPK activation." (PMID 33019697, 2020).
Hyperglycemia (continued). "Similar to pancreas-specific loss of BMAL1, we observed significant hyperglycemia without a concomitant increase in insulin, and PdxCre;Clockflx/flx mice were glucose intolerant and displayed reduced insulin secretion following a glucose challenge compared with their littermate controls." (PMID 32616519, 2020). "We hypothesized that the consumption of acid hydrolyzed silk peptides might alleviate hyperglycemia by improving insulin sensitivity and potentiating glucose-stimulated insulin secretion in a non-obese insulin-insufficient partial pancreatectomized (Px) rat model of Asian T2DM." (PMID 31991596, 2020). "Besides, since the T2D group was treated with glucose-lowering drugs (most of them with metformin) and some of them with insulin and they still had hyperglycemia, it would have been relevant to compare our current findings with a group of T2D patients with well controlled blood glucose levels." (PMID 32375786, 2020). "In addition to improvements in both insulin sensitivity and secretion, there is evidence for the benefits of EA in decreasing postprandial hyperglycemia (via inhibition of intestinal α-glucosidase activity) and, to a lesser extent, the modulation of incretin effect." (PMID 33287432, 2020). "The factors that increased the incidence of hospitalization after an ED attendance for acute hyperglycaemia were being treated with insulin, doubling the risk (IR = 2.00, 95% CI 1.31–2.05), and not having performed a yearly HbA1c test (IR = 1.37, 95% CI 1.10–1.72)." (PMID 32429960, 2020). "Furthermore, in addition to improved glucose tolerance and insulin sensitivity, as well as lower plasma insulin concentration detected in Stk25-KO mice in this study, we previously also observed reduced hyperglycemia in high-fat diet–fed Stk25–/– versus WT mice." (PMID 33170807, 2020). "Insulin resistance may lead to hyperglycemia and decreased tissue responsiveness to the biological activity of insulin, a metabolic problem that induces catabolic state and may lead to increased morbidity, prolonged hospital and intensive care unit (ICU) stay and decreased survival." (PMID 33053694, 2020). "This hyperglycaemia is associated with insufficient or no circulating insulin." (PMID 33102403, 2020). "Interestingly, intranasal insulin treatment in insulin-deficient mice was shown to ameliorate synaptic degeneration and deficits in learning and memory, without preventing hyperglycemia." (PMID 32265637, 2020). "In addition, stress hormone change in GDM women could reduce insulin secretion and was also positively correlated with IR, both of which lead to significant and persistent hyperglycemia in GDM women." (PMID 32066661, 2020). "Therefore, this study aimed to retrospectively assess whether Dula could safely improve GC-induced hyperglycemia and lower insulin injection frequency and dose." (PMID 32381085, 2020). "Several metabolic perturbations have been linked to the pathogenesis of peripheral DN (including hyperglycemia, dyslipidemia, oxidative stress, altered levels of insulin and neurotrophic factors, polyol-pathway flux, non-enzymatic glycation, and inflammatory stress." (PMID 31451429, 2019). "Interestingly, different from the previous case, also the minimum glucose level Gmin improves (increases) with Δ and Gmax: this is a consequence of the fact that we are using both insulin and glucagon as control inputs, which enables us to avoid both hypoglycemia and hyperglycemia." (PMID 30893335, 2019). "In our experimental conditions, the significant increase of plasmatic and pancreatic LOOH and nitrite/nitrate levels, markers of oxidative/nitrosative stress, induced by low insulin content and consequent hyperglycemia, may be related to upregulation of pancreatic iNOS protein." (PMID 31108850, 2019). "Thus, hyperglycemia and an increased caloric intake may have a proinflammatory effect, whereas insulin could exert anti-inflammatory properties." (PMID 31052277, 2019).
Hyperglycemia (continued). "However, maintenance of euglycemia throughout surgery is quite challenging; intermittent blood glucose measurement cannot guarantee avoidance of hyperglycemia and hypoglycemia due to the time lag between recognition of the blood glucose level and administration of glucose or insulin." (PMID 32025979, 2019). "Thus, although type 2 diabetes and GSDI appear to be opposite diseases in terms of glucose production and insulin sensitivity, the liver is chronically exposed to either hyperglycemia or G6P accumulation, respectively, leading the same metabolic consequences, in particular hepatic steatosis." (PMID 31756997, 2019). "The paradox of arterial glucose management in TBI is that whereas hyperglycemia per se is associated with poor outcome and deranged neurophysiology, tight glycemic control with intensive insulin therapy (IIT) management to normoglycemia has failed to reduce mortality and improve outcome in TBI." (PMID 31123993, 2019). "At 36 h after the cessation of all insulin administrations, insulin levels fell to 2500 μU/mL and glucose levels were elevated and remained over 360 mg/dL (20 mmol/L) throughout the day, indicating supplemental insulin, either exogenous or endogenous, to be necessary for prevention of hyperglycemia." (PMID 30621663, 2019). "However, the NGR which were supplemented with PFB were spared from these neurologic impairments in addition to the reduction in diabetic metabolic impairment including better overall glucose control, less hyperglycemia, better insulin levels and less insulin resistance as previously reported." (PMID 31819070, 2019). "Moreover, the significant increase of plasmatic and pancreatic LOOH induced by low insulin content and consequent hyperglycemia may be related to downregulation of pancreatic antioxidant defenses, both enzymatic and nonenzymatic, such as HO-1, GGCL, and RSH." (PMID 31108850, 2019). "In the current study, we investigated the effect of TRPV1 blockade on hyperglycemia indirectly by assessing oral glucose tolerance (i.e., the ability to clear orally administered glucose), both as a direct measurement of blood glucose and the insulin response to oral glucose." (PMID 31344877, 2019). "Hyperglycemia induces the increase of ROS production, which in turns causes damages in cells and activation of inflammation processes and triggers apoptosis in the β-cells, worsening the lack of insulin." (PMID 31064136, 2019). "Thus, olanzapine may induce hyperglycemia in clinical settings by suppressing insulin secretion from pancreatic β-cells through inhibition of dopamine D3, serotonin 5-HT2B and 5-HT2C, and histamine H1 receptors." (PMID 31712714, 2019). "In fact, intrauterine exposure to hyperglycemia determines an impairment in placental cholesterol uptake and alters placental methylation of leptin and adiponectin, hormones that regulate energy balance and insulin sensitivity, leading to the development of both leptin and insulin resistance." (PMID 31572434, 2019). "The effect of sustained, moderate hyperglycemia is here exerted exclusively on β-cell replication, hence on the maintenance of β-cell mass: should there be reasons to assume that a toxic effect is also exerted on insulin secretory mechanisms, this ought to be incorporated in the model." (PMID 31600232, 2019). "However, induction of hyperglycemia in vivo influences insulin production and levels, which impacts myocardial ischemia–reperfusion injury and may influence myocardial glucose uptake and O-GlcNAc levels differently in T2DM and non-diabetic hearts." (PMID 31151453, 2019). "Besides, animal experiments have demonstrated that AD-MSC infusion could improve hyperglycemia through recovery of islet β cells, reduction of inflammation, and improvement of insulin sensitivity." (PMID 31455405, 2019). "However, recent results show that lycopene may increase insulin sensitivity and prevent hyperglycemia through inhibition of the STAT-3/SREBP-1c pathway." (PMID 31223502, 2019).
Hyperglycemia (continued). "Based on this model, we design infusion rates of either insulin (monotherapy) or insulin and glucagon (dual therapy) that can optimally maintain the blood glucose level within desired limits after consumption of a meal and prevent the onset of both hypoglycemia and hyperglycemia." (PMID 30893335, 2019). "In addition, since resveratrol also impairs the intestinal absorption of glucose (by inhibiting α-glucosidase), and favours glucose utilization in skeletal muscles, its prolonged administration results in limiting hyperglycaemia and facilitating glucose homeostasis regulation by insulin." (PMID 30917543, 2019). "Next, we wondered whether the vagus nerve controls hyperglycemia by inducing insulin." (PMID 30700738, 2019). "With regard to insulin, a vicious cycle is likely to be present between persistently high HbA1c level and insulin resistance, whereby an increased dose is necessary to control hyperglycemia leading to further weight gain, resulting in a further increase in CVD risk." (PMID 31877127, 2019). "In contrast, short duration high intensity aerobic or anaerobic activity, a pattern typical of children's natural play, may maintain glucose levels during exercise and even result in early post-exercise hyperglycemia if performed while plasma insulin is close to basal level." (PMID 31258513, 2019). "The treated rats showed an improvement of hyperglycemia and glucose tolerance, which may be due to the increased utilization of glucose in the liver via an improvement of insulin sensitivity or a restoration of hepatic glucokinase and glycogen storage activity." (PMID 31340583, 2019). "As indicated in our prior longitudinal NOD study, onset of hyperglycemia profoundly altered the overall metabolic landscape affecting the corresponding pathways, even though, hyperglycemia was partially controlled in the diabetic animals using sustained release insulin implants." (PMID 31569489, 2019). "Interestingly, EPA treatment improved postprandial hyperglycemia, insulin secretion ability and hypertriglyceridemia, that might have beneficial effects on endothelial function and oxidative stress." (PMID 29452596, 2018). "A substantial hyperglycaemia level may overcome local or general microcirculation disturbances (injuries, sepsis, ischaemia) by increasing the concentration gradient, which facilitates non-insulin-dependent glucose uptake." (PMID 30005711, 2018). "In addition, in adult but not in young rats, the hyperinsulinemia was associated with hyperglycemia, thus suggesting that there is a progressive decrease of whole body insulin sensitivity with aging." (PMID 29755364, 2018). "However, hyperglycemia is still not rare because the extent of hepatocyte ischemia reperfusion injury is profound and insulin sensitivity is impaired due to underlying chronic liver disease, surgical stress, vasoactive drugs, and steroid immunosuppression." (PMID 30390037, 2018). "Interestingly, despite a previous report indicating that mice expressing Neurog3 under the control of the insulin promoter would die shortly after birth due to hyperglycemia, InsCre::Neurog3OE double transgenics were viable, fertile, healthy, and displayed normal basal glycemia (data not shown)." (PMID 30092080, 2018). "Differences in hyperglycemia between surgical services could be explained by not only whether basal-bolus insulin therapy was used but also by differences in the amplitudes and frequencies of the changes in insulin doses." (PMID 29255628, 2018). "Thus, in insulin-resistant conditions, a decrease in the blood glucose clearance occurs, while the hepatic glucose output and release in the plasma persist, contributing to the hyperglycemia, namely high glucose levels in the bloodstream." (PMID 29535681, 2018). "Indeed, hyperglycaemia and IR were reduced by enhancement of insulin muscular sensitivity." (PMID 30305835, 2018).
Hyperglycemia (continued). "Finally, by treating hyperglycemia and by favoring hypoglycemia, both exenatide and insulin could have lowered the activation of the cardioprotective pathways." (PMID 30384842, 2018). "Furthermore, both cord-blood insulin as well as leptin > 90th percentile showed strong positive associations with maternal 3rd trimester hyperglycemia, but neither with pregravid BMI nor excessive GWG." (PMID 29925339, 2018). "However, inappropriately reduced BCL11A expression could also result in a pathological sequence of chronic, relatively increased insulin secretion, leading to insulin resistance, beta cell exhaustion, and eventual hyperglycemia." (PMID 30242153, 2018). "Thus, in this study it was seen that the association of both agents (Vildagliptin and Quercetin) in a formulation was able to improve the hyperglycemic condition and promote a 70% reduction in hyperglycemia in relation to the 54.5% improvement achieved by treatment with insulin." (PMID 30333575, 2018). "This could lead to the risk of hypoglycemia and a lower requirement of insulin (however, it should be noted that exercise could cause hyperglycemia in the absence of insulin)." (PMID 30363935, 2018). "Immediate treatment of hyperglycemia using basal insulin in this early post-transplant phase has been shown to prevent later development of PTDM in our previous proof-of-concept Treat-to-target Trial of Basal Insulin in Posttransplant Hyperglycemia (TIP study)." (PMID 29518094, 2018). "From this perspective, in addition to the insulin signaling, it is crucial to consider also metabolic pathways in this search, examining key metabolic regulators and coordinators that may have a role in the onset of hyperglycemia." (PMID 29535681, 2018). "Sustained hyperinsulinemia and hyperglycemia with compromised insulin/IRS2/FOXO1 signaling yields high expression of MTP and apoC-III with an overproduction of TG-VLDL1 yet causes of compromised insulin/IRS2/FOXO1 signaling remain unclear." (PMID 28550272, 2018). "A study from 33 years ago reported that insulin injection therapy was required in 50% of renal transplant recipients who were given high-dose GC therapy while a recent study indicated that nateglinide and acarbose improved postprandial hyperglycemia in patients with GC-DM." (PMID 30285859, 2018). "Thus, under hyperglycemia, fatty acids and insulin reduce oxidative stress in β-cells." (PMID 29813102, 2018). "Therefore, the higher basal LGR may be the result of increased liver glycogenolysis, as glycogen stores could be enhanced because of the long-term hyperglycemia, the predominant feature of non-insulin treated T1DM." (PMID 30517288, 2018). "For example, if the hypothesis “patient has hyperglycemia” is true, the process updates the plan and adds 18 hypotheses according to the rules, such as “the latest insulin intake was lower than the insulin needed defining by the sensitivity factor for reaching 5.5 mmol/L”." (PMID 30291097, 2018). "Patients with moderate degrees of hyperglycaemia, patients without previous insulin therapy and elderly or frail patients at high risk of hypoglycaemia may be treated with a combination of DPP4i and basal insulin according to a recent therapeutic algorithm." (PMID 30208631, 2018). "Thus, the exaggerated hyperglycemia in response to the glucose challenge during VNS may be explained by VNS‐induced inhibition of glucose‐stimulated pancreatic insulin secretion." (PMID 30569658, 2018). "However in women with COPD-BS were observed higher levels of insulin and leptin, which seems not be enough to diminish hyperinsulinemia and hyperglycemia, which the high risk of develop T2DM and other pathogenic effects is maintained." (PMID 30514305, 2018). "In addition, a growing database of cell culture and animal studies indicates that ginseng may alleviate hyperglycemia by enhancing pancreatic beta cell function and reducing insulin resistance." (PMID 28954411, 2017).